BCL2 (BCL2 apoptosis regulator)
Diseases named in the same sentence as BCL2 in open-access papers (continued):
Sharing a sentence is not in itself a finding about the gene and the disease.
Sepsis (continued). "In two separate mouse models, the over-expression of BCL2 during sepsis was protective against the death of both lymphoid (thymocytes and splenic T cells) or myeloid cells (dendritic cells and macrophages), and was important for host immune responses during sepsis." (PMID 32479514, 2020). "In addition, a recent study has shown that overexpression of B-cell lymphoma 2 (Bcl-2) could dispel sepsis-induced depletion of DCs, suggesting that the proteins involved in apoptosis play an important role in DC loss during sepsis." (PMID 29075648, 2017). "However, treatment with GA could downregulate the expression of cleaved caspase-3 and upregulate the ratio of Bcl-2/Bax, compared with sepsis group." (PMID 26904148, 2016). "However, in patients with sepsis, Bcl-2 protein levels dropped by about 25%." (PMID 18925930, 2008). "In our study, 6 key target genes involved in sepsis and COVID-19 treatment with JHD were identified including AKT1, MMP9, ICAM1, TLR4, BCL2 and HIF1A based on PPI network." (PMID 41411324, 2025). "The gene differential expression analysis showed that compared with the healthy group, the sepsis patient group exhibited significantly lower expression levels of AKT1 and BCL2, but significantly higher expression levels of MMP9, ICAM1, TLR4, and HIF1A." (PMID 41411324, 2025). "Macrophage-specific ADAM8 CKO mice exhibited preserved cardiac function, reduced myocardial injury markers, attenuated apoptosis (decreased Bax/Bcl2 ratio), and enhanced survival in both LPS-induced and CLP sepsis models." (PMID 41169382, 2025). "This pluripotent cytokine can mitigate lymphocyte apoptosis by enhancing the expression of anti-apoptotic proteins such as Bcl-2, CD-28, boosting IFN-γ levels, and increasing TCR diversity, which are typically diminished in patients with sepsis." (PMID 39720718, 2024). "In the GSE13904 dataset, the expression trends of BCL2 and FASLG showed a significant decrease in sepsis, while JAK3 exhibited elevation." (PMID 38894720, 2024). "Following the induction of sepsis (CLP group), Bcl-2 expression significantly plummeted, indicating a considerable increase in cell apoptosis." (PMID 38546748, 2024). "Except for CYP4V2, there were also three genes down-regulated in sepsis, including ALOX15, BCL2, and FTO." (PMID 36820206, 2023). "In the present study, we identified 47 DE-NRGs between sepsis and healthy control in the dataset GSE65682 and screened out 4 hub genes (BACH2, GATA3, LEF1, and BCL2) via various machine learning algorithms." (PMID 37091800, 2023). "In this study, we investigated the role of lncRNA SNHG1 in sepsis‐induced myocardial injury and illustrated that lncRNA SNHG1 promoted sepsis‐induced myocardial injury by regulating the DNMT1/Bcl‐2 axis." (PMID 35678255, 2022). "In sepsis mouse models pretreated with Gln, the activation of CD4+ T cells was in equilibrium, and the expression of the anti-apoptotic protein Bcl-2 was more pronounced." (PMID 36211442, 2022). "Menthol markedly suppressed sepsis induced elevation of tissue TNF-a, ameliorated sepsis-induced cleavage of caspase-3 and restored the antiapoptotic marker Bcl2." (PMID 35814769, 2022). "In our study, we found that Bax, caspase-3, and BIM expression levels decreased, whereas Bcl-2 expression increased, and the CD4+ T cell apoptosis rate decreased significantly in the lck-mTOR sepsis mice." (PMID 35915740, 2022). "Mcl-1 and Bcl-2 can prevent Fas-mediated PMN apoptosis and both are upregulated in PMN from patients with sepsis." (PMID 33262756, 2020). "As a crucial part of sepsis-related AKI, we examined cell apoptosis in renal tissues, especially the expression of cleaved caspase-3, PARP, and Bcl-2/Bax, and demonstrated an antiapoptosis effect of MRS treatment." (PMID 30581532, 2018). "Treatment with SP600125 decreased BAX expression and enhanced BCL-2, thus suggesting the specific JNK inhibitor blunts the activation of proapoptotic signal in polymicrobial sepsis." (PMID 25873765, 2015).
Sepsis (continued). "The Bcl-2/Bax ratio, cleaved caspase-3, caspase-9, and PARP protein expressions in the liver tissues were upregulated during sepsis and normalized after rhHsp72 treatment." (PMID 26221596, 2015). "The importance of immune cell apoptosis in the pathogenesis of sepsis can be underscored by the observations that Bcl-2 overexpression or treatment with z-VAD-fmk, a pan-caspase inhibitor, improves survival in mouse models of sepsis." (PMID 26322041, 2015). "In previous studies in a murine model of sepsis induced by cecal ligation and puncture (CLP), we found that intraperitoneal (ip) instillation of myeloid cells over-expressing BCL2 protected normal mice against death following CLP." (PMID 20161703, 2010). "Our research results demonstrate that ECG alleviates sepsis-induced ALI by inhibiting the NLRP3/Caspase-1/GSDMD signaling pathway-mediated pyroptosis, the Bcl-2/Bax/Caspase-3 signaling pathway-mediated apoptosis, and regulating the ZBP1/MLKL/RIPK1 signaling pathway-mediated necroptosis." (PMID 41496909, 2025). "More importantly, a cohort study in pediatric intensive care unit (PICU) showed patients, who developed sepsis and/or multiple organs dysfunctions (MODS), had lower lymphocytic counts and lower levels of BCL2 comparing to control group, which provided additional proof covering different age groups." (PMID 38894720, 2024). "In a mouse model of sepsis, IL-15 has been shown to attenuate sepsis-induced apoptosis of natural killer (NK) cells, dendritic cells, and CD8+ T cells by increasing the expression of the anti-apoptotic protein Bcl-2, and decreasing the expression of pro-apoptotic proteins Bim and PUMA." (PMID 39720718, 2024). "Curcumin in sepsis reduced cerebral mitochondrial dysfunction (MMP, ROS, and mitochondrial complex activity I), apoptosis in neurons, and expression of BAX and increased the expression of BCL-2." (PMID 36756300, 2023). "However, Bax, caspase-3, and BIM were upregulated, the expression levels of Bax, caspase-3, and BIM were upregulated, the BCL-2 expression level was downregulated, and the CD4+ T cell apoptosis rate significantly increased in the lck-TSC1 sepsis mice." (PMID 35915740, 2022). "This study also verified excessive apoptosis in the intestinal epithelium, which was characterized by elevated expression of Bax and cleaved caspase 3, decreased Bcl2 expression and an increase in TUNEL-positive cells, which was accompanied by mitochondrial dysfunction during sepsis." (PMID 36581806, 2022). "Both the in vivo and the in vitro data suggest that the GSS has anti‐apoptotic effects on LPS‐induced lung vascular EC injury via TLR4/ Myd88/NF‐κB/BCL‐2 signalling, which may be the main reason why GSS effectively alleviates sepsis‐induced ALI." (PMID 31756053, 2020). "Furthermore, we found that GSS not only significantly reversed sepsis‐induced BCL‐2 decreases in mouse lung tissue but also inhibited lung vascular barrier disruption and ALI in sepsis." (PMID 31756053, 2020). "Interestingly, in genetically engineered mice that are resistant to apoptosis due to transfection with the anti-apoptosis gene Bcl-2, sepsis results in uniquely decreased transcription of CEACAM1 in splenocytes and increased sepsis survival." (PMID 23894299, 2013). "While we observed differential gene expressionof Bcl-2 and Bim in patients with sepsis, these effects were not obvious immediately after surgery in the initial stages of infection." (PMID 21711552, 2011). "To further determine whether 6 key target genes identified in this study (AKT1, MMP9, ICAM1, TLR4, BCL2, and HIF1A) could be used as therapeutic targets for sepsis and COVID-19, we downloaded the gene expression profiles of sepsis and COVID-19 patients from the GEO database (GSE95233, GSE171110)." (PMID 41411324, 2025). "BCL2, FASLG, IRF9 and JAK3 might be key regulatory genes affecting apoptosis in sepsis." (PMID 38894720, 2024).
Sepsis (continued). "Additionally, the roles of targets such as CASP1/3, BCL2, and MTOR in sepsis have been discussed." (PMID 39584444, 2024). "However, 2-DG inhibited the expression of Bcl-2 and Bax during sepsis; LY294002 did not affect Bax expression even after IFNγ treatment." (PMID 37434129, 2023). "Further experimental studies showing that overexpression of Bcl-2 (B-cell lymphoma 2) in T or B cells can prevent lymphocyte apoptosis in sepsis support these results, as Bcl-2 may inhibit the mitochondrial but not the receptor-mediated apoptosis pathway." (PMID 36279072, 2022). "In addition, DEX dramatically prevented sepsis-induced pulmonary cell apoptosis in mice, as reflected by decreases in the number of TUNEL-positive cells, the protein expression of cleaved caspase-9 and cleaved caspase 3 and the Bax/Bcl-2 ratio." (PMID 31927655, 2020). "Many of these findings (increased oxidative stress, HIF-1α and bcl-2 expression after isoflurane exposure) are consistent with prior work on APC and may play a role in the organ protection observed by previous authors during sepsis." (PMID 31307382, 2019). "Indeed, a recent study which separated lymphocytes from monocytes prior to RT-MLPA, showed differential levels of Bcl2 in patients with sepsis compared to controls in the lymphocyte but not monocyte populations." (PMID 21966464, 2011). "During sepsis, LPS binding to TLR-4 may activate the JNK, ERK, or p38 MAPK pathways or the mitochondria-mediated intrinsic apoptosis pathway, which in turn activates caspase-3, an apoptosis activator effector, and downregulates Bcl-2, an inhibitor of apoptosis." (PMID 37900081, 2023). "Interestingly, our study showed that CAIF suppressed LPS‐induced cardiomyocyte apoptosis, reduced Bax and cleaved caspase 3 levels, and increased Bcl‐2 expression, indicating that CAIF may play a protective role in sepsis‐induced CHF by inhibiting cell apoptosis." (PMID 34547186, 2021). "Downregulation of BCL2 and BBC3 gene expression was observed in sepsis patients (p < 0.05), but not in uncomplicated infection, potentially contributing to differences in the severity of metabolic impairment." (PMID 41704334, 2026). "Given that the BCL2 BH4-domain proteins themselves do not appear to elicit a pro-inflammatory response, as is observed with many other DAMPs, it is possible that extracellular administration of rhBCL2 or rhBCL2A1 protein may offer a new approach to therapy of sepsis." (PMID 21390214, 2011).
liver cancer (149 papers, 2006 to 2026). An epithelial or non-epithelial malignant neoplasm that arises from the liver. "Treatment with SS-b2 (40 or 80 mg/L) for 24 h caused a steady decrease in the protein expression of Bcl-2 in HepG2 liver cancer cells, whereas the expression of Bax, Cyt-c, cleaved caspase 9 and cleaved caspase 3 dramatically increased." (PMID 39544485, 2024). "Such a polysaccharide develops activity through an apoptosis-associated pathway by modulating the expression of Bax, Bcl-2, and caspase-3 and has been proposed as a potential therapeutic agent (or chemosensitizer) for liver cancer therapy." (PMID 39064945, 2024). "Cancer literatures proved that miR-22-3p targets SP1, inhibits the expression of downstream genes CCND1 and BCL2, thereby inhibiting the growth of liver cancer cells, and the low expression of miR-22-3p is associated with metastatic liver cancer." (PMID 35011220, 2022). "The upregulation of BCL2 mRNA in our study suggests that changes causing resistance to doxorubicin may affect the mitochondrial apoptotic pathway in liver cancer cell lines." (PMID 40216647, 2025). "Expression of ILF2 may regulate cell growth and apoptosis in liver cancer cells via regulation of B-cell lymphoma 2 (Bcl-2), Bcl-2 related ovarian killer (Bok), Bcl-2-associated X protein (BAX), and cellular inhibitor of apoptosis 1 (cIAP1)." (PMID 27556459, 2016). "Of them, BCL2 is a key protein in the cancer pathway, the activation of BCL2/BAX protein in cells can promote the apoptosis of liver cancer cells." (PMID 40230723, 2025). "Disruption of mitochondrial membrane potential (MMP) induces apoptosis in liver cancer cells, inhibits their proliferation, downregulates membrane fluidity, and suppresses the expression of the anti-apoptotic protein Bcl-2." (PMID 40429833, 2025). "Cationic nanoparticle complexes encapsulating paclitaxel and the Bcl-2 gene have been shown to inhibit drug-resistant liver cancer cells by disrupting P-glycoprotein (P-gp) drug efflux and activating apoptotic pathways." (PMID 39757310, 2025). "Rosmarinic acid derived from Rubus chingii induces apoptosis in gastric and liver cancer cells via mitochondrial signaling pathways, influencing Bcl-2, Bax, cytochrome C, and caspase-3." (PMID 41227657, 2025). "Dryocrassin ABBA, a phloroglucinol derived from Dryopteris crassirhizoma, induces apoptosis in liver cancer cell lines by simultaneously inhibiting BCL-2 expression and increasing Bax expression." (PMID 40004995, 2025). "Pharmaco-logically, Gentiana extracts target NF-κB and MAPK pathways to suppress in-flammation and oxidative liver injury via Nrf2 activation, while inducing tumor cell apoptosis (Bax/Bcl-2) and S/G2-M phase arrest to inhibit lung/liver cancer proliferation." (PMID 41194879, 2025). "The natural compound curcumin, in combination with fluorouracil, induces apoptosis via the downregulation of BCL2 and the upregulation of cleaved caspase-9 and caspase-3 in liver cancer cells." (PMID 39765861, 2024). "In order to explore the molecular mechanism by which ITGAV promotes tumorigenesis of liver cancer, the protein expression of BCL2, PXN, and MAPK was detected after overexpression and knockdown of ITGAV." (PMID 38374893, 2024). "Collectively, these findings illustrated that flavokawain C promoted apoptosis in liver cancer cells through concurrent modulation of Bcl2 and Bax protein expression." (PMID 38460052, 2024). "In many human tumors, including colon, lung, prostate, neuroblastoma, stomach, lymphoma, breast, and liver cancer, the level of Bcl-2 proteins is increased." (PMID 39188653, 2024). "An increase in apoptotic cell death upon knockdown of BubR1 has previously been reported in liver cancer, resulting in cleaved caspase 3, and Bax was elevated, but Bcl-2 was reduced, and in thyroid cancer, caspase 3, 7, and 9 were increased." (PMID 39062183, 2024).
liver cancer (continued). "The findings demonstrated that SS-b2 exerts an anticarcinogenic effect on the HepG2 liver cancer cells, resulting in a reduction in the expression of the antiapoptotic protein Bcl-2 and an increase in the expression of the proapoptotic protein BAD." (PMID 39544485, 2024). "CRPBT can significantly down-regulate the phosphorylation of PI3K and AKT in liver cancer cells, up-regulate the Bax/Bcl-2 ratio, and inhibit the expression of MMP2/3, N-cadherin and Vimetin proteins." (PMID 36865794, 2023). "As a result, SM is believed to inhibit liver cancer cell proliferation and induce apoptosis by activating the Bcl-2/Bax and caspase signaling pathways." (PMID 38192621, 2023). "The current study found that the PI3K/AKT/mTOR and the caspase-3/Bax/Bcl-2 signaling pathways involved B. coagulans MZY531 mediated inhibition of liver cancer progression." (PMID 37705007, 2023). "Consistently, we observed positive correlation between KDM1A and BCL2 protein levels in liver cancer patients." (PMID 35970393, 2022). "Following treatment for 48 h, with increasing DATS concentration, the expression of Bax in liver cancer HepG2 cells showed an upward trend, and the expression of Bcl-2 revealed a downward trend." (PMID 37868628, 2022). "Similar reports showed that in the mouse liver cancer model, AG induced liver cancer cell apoptosis via up regulating the ratio of Bax/Bcl-2, triggering the cleavage of Caspase-3 and poly adenosine diphosphate ribose polymerase." (PMID 35747689, 2022). "In SMMC-7721 liver cancer cells, luteolin increased caspase-8 and decreased Bcl-2, and in Hep-G2 cells, it was reported that apoptosis was induced through BAX/BAK mitochondrial translocation and JNK activation." (PMID 36142874, 2022). "In comparison with the blank group, LFE regulated the mRNA expression levels of PTEN, PI3K, AKT, PDCD4, VEGFA, Caspase 9, Caspase 3, Bcl-2, Bax and Bad in liver cancer cells to different degrees." (PMID 36110518, 2022). "ABT-199 (venetoclax) is the first-in-class selective B-cell lymphoma 2 (BCL2) inhibitor, which is known to be ineffective towards liver cancer cells." (PMID 36386146, 2022). "An increase in Hint1 expression by Taraxasterol inhibits the growth of liver cancer cells and regulates Bax, Bcl2, and cyclin D1 expression in human liver cancer." (PMID 33671384, 2021). "For example, MRX34, a miR-34 mimic targeting forkhead box P1 (FOXP1) and BCL2, entered a multicenter phase I trial in 2013 for patients with primary liver cancer and small cell lung cancer." (PMID 32862195, 2021). "Reliably, the activation of CASPASE-3 and an antagonist of BCL-2 inhibits the potential intrusion of HepG2 liver cancer cells." (PMID 35009072, 2021). "In this study, EO potentially inhibited the BCL-2 mRNA and protein expression in HepG2 liver cancer cell lines." (PMID 35009072, 2021). "Another study indicated that the expression of Bcl-2 decreased, while the expression of Bax increased with the development of liver cancer." (PMID 34436030, 2021). "The relationship between Bcl-2/Twist1 and Bcl-2-Bmi1 promotes EMT and development of VM through loss expression of E-cadherin and increased vimentin expression in hepatic cancer cells." (PMID 31993365, 2019). "In this study, we prepared the GH-DPP nanoparticles for co-delivery of DOX and Bcl-2 siRNA for liver cancer therapy." (PMID 30723405, 2019). "The western blotting analysis also showed that DOP-40, DOP-60, and DOP-70 induced apoptosis in HepG2 human liver cancer cells through the Bcl-2 and Bax-dependent pathway." (PMID 30255241, 2018).